MPHOSPH9 (M-phase phosphoprotein 9)
Description:
Negatively regulates cilia formation by recruiting the CP110-CEP97 complex (a negative regulator of ciliogenesis) at the distal end of the mother centriole in ciliary cells. At the beginning of cilia formation, MPHOSPH9 undergoes TTBK2-mediated phosphorylation and degradation via the ubiquitin-proteasome system and removes itself and the CP110-CEP97 complex from the distal end of the mother centriole, which subsequently promotes cilia formation.
Synonyms: MPP9; MPP-9
Tractability: Antibody: UniProt places it where antibodies can reach, with high confidence. PROTAC: UniProt records ubiquitination sites on it; ubiquitination databases record sites on it.
Gene: Protein-coding gene on chromosome 12 (123,152,320 to 123,244,014, reverse strand). Ensembl gene ENSG00000051825.
Subcellular location: Cytoplasm, cytoskeleton, microtubule organizing center, centrosome, centriole; Golgi apparatus membrane; Cytoplasm, cytoskeleton, microtubule organizing center, centrosome
Subcellular location (Human Protein Atlas): Cytosol; Plasma membrane; Basal body; Centrosome; Golgi apparatus; Nucleoplasm
Gene Ontology:
Molecular function: protein binding
Biological process: negative regulation of cilium assembly
Cellular component: centriole; centrosome; ciliary basal body; Golgi apparatus; membrane; Golgi membrane
Genetic constraint (gnomAD): Loss-of-function variants: 66 observed, 116.19 expected, observed/expected ratio (o/e) 0.57, 90% interval 0.47 to 0.7. The upper end of that interval is the gene's LOEUF score, 0.7, which puts it in group 2 of 6, group 1 being the genes least tolerant of losing a copy. Missense variants: 1,099 observed, 1,275.8 expected, observed/expected ratio (o/e) 0.86, 90% interval 0.82 to 0.9. Synonymous variants: 389 observed, 449.33 expected, observed/expected ratio (o/e) 0.87, 90% interval 0.8 to 0.94.
Homologues: Orthologues: chimpanzee MPHOSPH9 (99% identical), macaque MPHOSPH9 (89% identical), dog MPHOSPH9 (86% identical), pig MPHOSPH9 (84% identical), rat Mphosph9 (73% identical), mouse Mphosph9 (72% identical), guinea pig MPHOSPH9 (62% identical), tropical clawed frog mphosph9 (37% identical).
Diseases named in the same sentence as MPHOSPH9 in open-access papers:
MPHOSPH9 is named in the same sentence as 33 diseases in open-access papers, as found by Europe PMC text mining. Sharing a sentence is not in itself a finding about the gene and the disease. The quoted sentences say what the papers report.
type 2 diabetes (4 papers, 2015 to 2022). "A study on the shared risk of schizophrenia and cardiometabolic diseases including obesity, body mass index, and type 2 diabetes suggested that MPHOSPH9, ARL6IP4, and SETD8 are pleiotropic risk genes." (PMID 36174000, 2022). "We examined the association of six SNP loci, rs6813195 near TMEM154, rs9505118 in SSR1, rs17106184 in FAF1, rs3130501 in POU5F1, rs702634 in ARL15, and rs4275659 near MPHOSPH9, identified by transethnic GWAS meta-analysis with susceptibility to type 2 diabetes in a Japanese population." (PMID 27115357, 2016). "Two adjacent genes MPHOSPH9 and SBNO1, located in 12q24, were reported as having susceptible associations with type 2 diabetes." (PMID 36174000, 2022). "We confirmed associations with type 2 diabetes for five of the seven SNPs (TMEM154-rs6813195, FAF1-rs17106184, POU5F1/TCF19-rs3130501, ARL15-rs702634 and ABCB9/MPHOSPH9-rs4275659)." (PMID 25799151, 2015). "We performed a replication study in a Japanese population to evaluate the association between type 2 diabetes and six susceptibility loci (TMEM154, SSR1, FAF1, POU5F1, ARL15, and MPHOSPH9) originally identified by a transethnic meta-analysis of genome-wide association studies (GWAS) in 2014." (PMID 27115357, 2016). "A trans-ethnic meta-analysis of type 2 diabetes genome-wide association studies has identified seven novel susceptibility variants in or near TMEM154, SSR1/RREB1, FAF1, POU5F1/TCF19, LPP, ARL15 and ABCB9/MPHOSPH9." (PMID 25799151, 2015). "Our results indicate that effects of the six SNP loci identified in the transethnic GWAS meta-analysis are not major among the Japanese, although SNPs in POU5F1 and MPHOSPH9 loci may have some effect on susceptibility to type 2 diabetes in this population." (PMID 27115357, 2016). "While there is a large literature linking MPHOSPH9 to health conditions such as type 2 diabetes and multiple sclerosis, this gene has not previously been linked to psychiatric conditions and may warrant further investigation." (PMID 31226868, 2019).
gastritis (2 papers, 2018 to 2024). Inflammation of the stomach. "Others included 41 GWS genes for GERD (Pgene-GERD < 2.62 × 10−6), 11 for PUD (Pgene-PUD < 2.62 × 10−6), three (RNF5, HLA-DQA1, and HLA-DQB1) for gastritis-duodenitis (Pgene-gastritis-duodenitis < 2.62 × 10−6), and three (HLA-C, PITPNM2, and MPHOSPH9) for IBS (Pgene-IBS < 2.62 × 10−6)." (PMID 38802514, 2024).
multiple sclerosis (2 papers, 2019 to 2021). A progressive autoimmune disorder affecting the central nervous system resulting in demyelination. "MPHOSPH9 was reported as a susceptible locus for multiple sclerosis." (PMID 33592582, 2021).
Obesity (2 papers, 2018 to 2022). Accumulation of substantial excess body fat. "Five of the twenty-one obesity-dependent DEGs are associated with obesity and insulin resistance (MPHOSPH9, BRCA1, ASP, ALCAM, GP2)." (PMID 30305020, 2018).
schizophrenia (2 papers, 2022). A major psychotic disorder characterized by abnormalities in the perception or expression of reality. "Genetic correlations between schizophrenia and cerebellar volume are observed in two loci that include MPHOSPH9 and GATAD2A as most significant signal in schizophrenia." (PMID 35842455, 2022).
myeloma (1 paper, 2016). "These includedmutations in the following genes: Sptn1, Mphosph9, andObscn, all of which have also been observed in human myeloma samplesusing whole genome sequencing." (PMID 26961797, 2016).
neuroblastoma (1 paper, 2010). Neuroblastoma (NB) is the most common solid, extracranial childhood tumor. "In addition to DIABLO, also ZCCHC8, RSRC2, KNTC1 and MPHOSPH9 showed statistically increased expression in neuroblastoma samples when compared to the groups of healthy samples." (PMID 20444257, 2010). "Using the in silico data mining approach, we identified elevated expression of five genes located at the 12q24.31 amplicon in neuroblastoma (DIABLO, ZCCHC8, RSRC2, KNTC1 and MPHOSPH9)." (PMID 20444257, 2010).
optic neuritis (1 paper, 2013). Optic neuritis is inflammation of the optic nerve, the nerve that carries the visual signal from the eye to the brain.The conditionmay cause sudden, reduced vision in the affected eye(s). "There were trends for associations of the TMEM39A and MPHOSPH9 polymorphisms with reduced odds of optic neuritis as well." (PMID 24130718, 2013).
MPHOSPH9 also shares sentences with these, for which no sentence is quoted: tumor (3 papers); asthma (2); gastric cancer (2); adult onset asthma (1); allergic disease (1); bacterial infection (1); childhood onset asthma (1); Cirrhosis (1); coronary artery diseases (1); COVID-19 (1); diabetes (1); duodenitis (1); endothelial dysfunction (1); gastric ulcer (1); gastrointestinal disease (1); infection (1); Insulin resistance (1); leukemia (1); nasal polyps (1); nonsmall cell lung cancer (1); Onset (1); preeclampsia (1); retinopathy of prematurity (1); Sepsis (1); Stroke (1).